XRCC6P1 (X-ray repair cross complementing 6 pseudogene 1)
Gene: Transcribed processed pseudogene on chromosome 10 (93,206,857 to 93,209,627, reverse strand). Ensembl gene ENSG00000237417.
Diseases named in the same sentence as XRCC6P1 in open-access papers:
XRCC6P1 is named in the same sentence as 4 diseases in open-access papers, as found by Europe PMC text mining. Sharing a sentence is not in itself a finding about the gene and the disease. The quoted sentences say what the papers report.
normal-tension glaucoma (1 paper, 2018). "Although the SNPs near MYOF and XRCC6P1 did not pass the Bonferroni-corrected threshold of P < 0.0125, rs4918865 was more strongly associated with the high-tension glaucoma (HTG) subset (P = 0.003 for HTG vs. P = 0.37 for normal-tension glaucoma (NTG)) in NEIGHBORHOOD." (PMID 29449654, 2018).
XRCC6P1 also shares sentences with these, for which no sentence is quoted: Corneal astigmatism (1 paper); glaucoma (1); myopia (1).